AMMECR1L (AMMECR1 like)
Synonyms: MGC4268
Tractability: PROTAC: ubiquitination databases record sites on it.
Gene: Protein-coding gene on chromosome 2 (127,861,630 to 127,885,967, reverse strand). Ensembl gene ENSG00000144233.
Subcellular location (Human Protein Atlas): Nucleoplasm; Cytosol
Gene Ontology:
Cellular component: nucleus
Genetic constraint (gnomAD): Loss-of-function variants: 4 observed, 35.6 expected, observed/expected ratio (o/e) 0.11, 90% interval 0.054 to 0.26. The upper end of that interval is the gene's LOEUF score, 0.26, which puts it in group 1 of 6, group 1 being the genes least tolerant of losing a copy. Missense variants: 231 observed, 408.98 expected, observed/expected ratio (o/e) 0.56, 90% interval 0.51 to 0.63. Synonymous variants: 145 observed, 154.67 expected, observed/expected ratio (o/e) 0.94, 90% interval 0.82 to 1.08.
Homologues: Orthologues: chimpanzee AMMECR1L (100% identical), dog AMMECR1L (99% identical), macaque AMMECR1L (99% identical), rabbit AMMECR1L (99% identical), pig AMMECR1L (99% identical), rat Ammecr1l (99% identical), mouse Ammecr1l (98% identical), guinea pig AMMECR1L (98% identical), tropical clawed frog ammecr1l (72% identical), Drosophila melanogaster CG5902 (43% identical), Caenorhabditis elegans R166.3 (28% identical). Paralogues in human: AMMECR1 (68% identical).